MED12 (mediator complex subunit 12)
Diseases named in the same sentence as MED12 in open-access papers (continued):
Sharing a sentence is not in itself a finding about the gene and the disease.
Uterine leiomyoma (74 papers, 2011 to 2026). The presence of a leiomyoma of the uterus. "This case describes a new, potentially targetable molecular alteration in a uterine leiomyoma, distinct from the common MED12-mutated pathway, highlighting the underlying molecular heterogeneity of these common tumors." (PMID 42137712, 2026). "In uterine leiomyomas, MED12 gene exon 2 mutations impair the normal function of the mediator complex, a key transcriptional regulator, leading to dysregulated transcriptome that promotes tumor growth (“gain of function”)." (PMID 41463261, 2025). "MED12 mutations trigger changes in enhancer architecture and transcriptional dysregulation typical of uterine leiomyomas." (PMID 40345582, 2025). "It has been shown that three main uterine leiomyoma molecular subtypes exist, including tumors with MED12 mutation, molecular aberrations leading to HMGA2 overexpression, and biallelic loss of FH." (PMID 37466765, 2024). "Most usual uterine leiomyomas (40–75%) are characterized by MED12 mutation, followed by 10–25% with HMGA2 overexpression." (PMID 37466765, 2024). "Genetic alterations associated with uterine leiomyoma are heterogeneous and they include mutations of mediator complex subunit 12 (MED12), overexpression of high mobility group AT-hook 2 (HMGA2), and inactivation of the fumarate hydratase (FH) gene." (PMID 38642139, 2024). "The other mutation of interest is in MED12, which is also seen in fibroadenoma, uterine leiomyomas, and leiomyosarcomas." (PMID 38993445, 2024). "Recent studies have focused on the role of MED12 mutation in the pathophysiology of uterine leiomyomas." (PMID 38279317, 2024). "Three main uterine leiomyoma molecular subtypes include tumors with MED12 mutation, molecular aberrations leading to HMGA2 overexpression, and biallelic loss of FH." (PMID 37466765, 2024). "This analysis confirmed that mutations in FH and MED12 co-exist for the first time in uterine fibroids in Australian women." (PMID 37113812, 2023). "Combining these three-patient case studies proves that MED12 and FH mutations co-exist, possibly driving and competing for the same roles in tumorigenesis of uterine fibroid." (PMID 37113812, 2023). "Recently, we identified 3% and 60% of uterine fibroids harbour specific mutations in MED12 exon 1 and exon 2 respectively of 65 uterine fibroids studied that were collected from Australian women." (PMID 37113812, 2023). "This evidence is in line with a mouse model study that the expression of missense mutant Med12 can be the sole cause of uterine fibroids." (PMID 37113812, 2023). "Recently, we reported MED12 exon 2 mutations in 39 out of 65 uterine fibroids (60%) from 14 Australian patients." (PMID 37113812, 2023). "It is intriguing that MED12 mutations are more frequent in uterine leiomyoma (up to 86%) than in uLMS (up to 22%)." (PMID 35326717, 2022). "Uterine leiomyomas are benign smooth muscle tumors that can be classified into at least three molecular subtypes, reflecting mutations in either MED12, HMGA2, or FH." (PMID 36068196, 2022). "While FH and COL4A5/6 mutations have been characterized, the majority of uterine leiomyoma (80–90%) harbor MED12 or HMGA2 alterations." (PMID 35203298, 2022). "Up to 86% of uterine leiomyomas have a mutation in MED12; however, only about 20% of uLMS harbour a mutation in this gene, indicating alternative origins for this rare tumour." (PMID 35326717, 2022). "Somatic mutations in Mediator complex subunit 12 (MED12m) have been reported as a biomarker of uterine fibroids (UFs)." (PMID 35618793, 2022). "In this study, uterine leiomyoma tissue samples from 15 women with confirmed MED12 p.Gly44Asp or p.Gly44Ser variants were analyzed for epigenetic changes." (PMID 33925166, 2021). "Mutations were detected in exon 2 of MED12 in 28 uterine leiomyoma samples (75% missense mutations and 25% in-frame deletions)." (PMID 34122542, 2021).
Uterine leiomyoma (continued). "Somatic mutations in MED12 have been implicated as the causal genetic lesion in the majority of uterine leiomyomas." (PMID 32094355, 2020). "Somatic mutations in this X linked gene impaired MED12 activities and were associated with several tumors, including uterine leiomyoma, breast fibroadenoma and prostate cancer." (PMID 31072327, 2019). "In uterine leiomyomas and breast fibroadenoma, MED12 mutations were found in the stromal cells and mainly located in the exon 2 region which led to the activation of the WNT pathway." (PMID 31072327, 2019). "Previous investigations clearly point to a number of different genetic subtypes of uterine leiomyomas with those affected by mutations of MED12 representing by far the most frequent sub-entity followed by that showing rearrangements of HMGA2." (PMID 29963223, 2018). "This study concludes that MED12 somatic mutations (44%) are by and large frequently observed in uterine leiomyomas of Saudi women." (PMID 30619444, 2018). "We recommend that mutation screening, particularly codon 44 of MED12 can assist in molecular diagnostics of uterine leiomyomas in majority of the patients." (PMID 30619444, 2018). "WNT4 is known to be overexpressed in uterine leiomyomas with MED12 mutations, and knock-down of MED12 in UL cells reduces WNT4 expression." (PMID 30226466, 2018). "MED12, a subunit of mediator complex genes is known to harbor genetic mutations, (mostly in exon 2), causal to the genesis of uterine leiomyomas among Caucasian, African American, and Asian women." (PMID 30619444, 2018). "Our study, being the first one from Middle Eastern Arab countries, confirms the trend of finding MED12 mutations in uterine leiomyomas." (PMID 30619444, 2018). "Uterine leiomyomas (UL) are the most prevalent symptomatic human tumors at all and somatic mutations of the gene encoding mediator subcomplex 12 (MED12) constitute the most frequent driver mutations in UL." (PMID 28410233, 2017). "A number of recent studies have reported mutations in exon 2 of the MED12 gene in most uterine leiomyomas." (PMID 28591699, 2017). "MED12 mutations have also been reported in other tumor types such as hematological cancers (chronic lymphoid leukemia), uterine leiomyomas, and uterine leiomyosarcomas." (PMID 27806318, 2016). "Analysis of 1,862 samples of major cancer types including sarcomas, colon, breast, and lung carcinomas and gastrointestinal stromal tumors, showed MED12 mutations exclusively in 52.2% (35/67) of uterine leiomyomas except for 0.3% (1/389) of colon carcinomas." (PMID 27806318, 2016). "MED12 was first implicated in human tumorigenesis when highly specific exon 2 mutations were identified in as many as 70% of uterine leiomyomas." (PMID 25595892, 2015). "A study of 18 uterine leiomyomas using exome sequencing identified recurrent somatic mutations in MED12 exon 2, and further investigation of 225 uterine leiomyomas revealed that, remarkably, 159 (71%) of the tumors harbored mutations." (PMID 25865354, 2015). "As in uterine leiomyomas, leiomyosarcomas, and breast fibroadenomas, all MED12 mutations in CLL are missense changes or small in-frame insertions and deletions." (PMID 25595892, 2015). "Exon 2 of MED12, a subunit of the transcriptional mediator complex, has been frequently mutated in uterine leiomyomas and breast fibroadenomas; however, it has been rarely mutated in other tumors." (PMID 25865354, 2015). "A number of recent studies have reported mutations in exon 2 of the MED12 gene in the majority of uterine leiomyomas (50–70%)." (PMID 25621995, 2015). "The vast majority of uterine leiomyomas (UL) either display clonal karyotype aberrations detected by classical cytogenetics or mutations of Mediator Subcomplex 12 (MED12), or both." (PMID 25506394, 2014). "Uterine leiomyoma is a common, benign, monoclonal, diploid smooth muscle tumor with a frequent mutation in mediator complex subunit 12 (MED12)." (PMID 23785396, 2013).
Uterine leiomyoma (continued). "Several recurrent genetic aberrations, such as trisomy of chromosome 12, deletions in 7q, and mutation affecting the mediator complex subunit 12 (MED12) or the high mobility group AT-hook 2 (HMGA2) gene were reported in uterine leiomyomas." (PMID 22570742, 2012). "The high MED12 exon 2 mutation frequency observed in uterine leiomyomas seem to associate with the location of the tumours in the uterus and also with their benign nature." (PMID 23132392, 2012). "Recently, we discovered through exome sequencing that as many as 70% of uterine leiomyomas harbour specific mutations in exon 2 of mediator complex subunit 12 (MED12)." (PMID 23132392, 2012). "We recently identified various somatic mutations in exon 2 of the mediator complex subunit 12 (MED12) gene, in as many as 70% of the studied uterine leiomyomas obtained from patients of Finnish (Caucasian) origin." (PMID 22182697, 2011). "The aim of this study was to investigate the frequency of MED12 exon 2 mutations in uterine leiomyomas of South African patients to confirm that MED12 has a major role in the genesis of this tumor type in populations other than Finns." (PMID 22182697, 2011). "MED12 exon 2 mutation is the most frequent mutation associated with uterine leiomyomas." (PMID 41493967, 2026). "Interestingly, MED12 is one of the most frequently mutated genes in uterine leiomyomas (approximately 70% of cases)." (PMID 40940746, 2025). "Future research may develop targeted therapies for uterine leiomyomas with the MED12 mutations, such as gene editing-based therapy." (PMID 40940746, 2025). "The driver gene MED12 mutation is also associated with the growth of uterine leiomyomas." (PMID 40385736, 2025). "Studies have demonstrated that from total genetic aberration, about 70%–80% of uterine leiomyoma’s shown site-specific somatic mutation on mediator complex subunit 12 (MED12) genes in different populations, including Finnish (Caucasian), northern United States regions, and South African women." (PMID 38572418, 2024). "Nearly 70% of Uterine fibroid (UF) tumors are driven by recurrent MED12 hotspot mutations." (PMID 37429859, 2023). "Another SNP on chromosome X (rs7052106), located between genes IL2RG and MED12, is associated with uterine fibroids and several other traits, including mean platelet volume, reticulocyte traits, and platelet distribution width, as well as total testosterone levels." (PMID 36579561, 2022). "Uterine fibroid (UF) driver mutations in Mediator complex subunit 12 (MED12) trigger genomic instability and tumor development through unknown mechanisms." (PMID 35418189, 2022). "The present results suggest that SRA1 may explain the phenotypic difference observed in the tumor sizes of uterine leiomyoma samples considering the MED12 mutation pattern." (PMID 34122542, 2021). "In support of this hypothesis, similar results were obtained when investigating transcriptional dysregulation in uterine leiomyoma samples with MED12 variants." (PMID 33925166, 2021). "In addition, uterine leiomyoma harbors genetic alteration of some driver genes including MED12 mutations, biallelic inactivation of FH, and HMGA2 rearrangements." (PMID 31988393, 2020). "In this study, we have estimated the expression level of CYP24A1 hsa_circ_0060927 in uterine leiomyoma and adjacent tissues considering the mediator complex subunit 12 gene (MED12) mutation profile by quantitative real‐time polymerase chain reaction (qRT‐PCRs)." (PMID 31746073, 2020). "Up to 86% of uterine leiomyomas harbour somatic mutations in mediator complex subunit 12 (MED12)." (PMID 28432313, 2017). "However, MED12 mutations cannot completely differentiate between uterine leiomyomas and normal myometrium." (PMID 27498619, 2016). "MED12 mutations were detected in approximately 70% of uterine leiomyoma samples." (PMID 27498619, 2016). "Highly specific MED12 mutations were first observed in benign uterine leiomyomas." (PMID 25595892, 2015).
Uterine leiomyoma (continued). "Frequent mutations in MED12 exon 2 in the phyllodes tumors suggest that it may share genetic etiology with uterine leiomyoma, a subgroup of uterine leiomyosarcomas and breast fibroadenoma." (PMID 25865354, 2015). "Recently MED12 mutations have been reported in uterine leiomyomas." (PMID 22768200, 2012). "All of the MED12 variants that we observed in uterine leiomyomas were heterozygous." (PMID 22428002, 2012). "Whole exome sequencing yielded MED12 as a candidate gene associated with uterine leiomyomas." (PMID 22428002, 2012). "Somatic mutations in exon-2 of the MED12 gene have been recently reported by several studies However, the prevalence of MED12 gene mutations and the functional roles of these mutations in the tumorigenesis of uterine fibroids in north Indian population remain unknown." (PMID 38572418, 2024). "Oncogenic anomalies in the N-terminal part of MED12 are the most common and occur in nearly 70% of uterine fibroid." (PMID 37113812, 2023). "MED12 is reported to be the most frequently altered gene in uterine leiomyomas, and changes in either MED12 or HMGA2 are present in 80%-90% of uterine leiomyomas." (PMID 35305104, 2022). "On the other hand, in Subtypes-2 and -3, the DNA methylation status in the autosomes tended to be hypermethylated compared to that in Subtype-1 and the MED12-positive uterine fibroids." (PMID 35618793, 2022). "Clinically, many articles have reported that MED12 is an oncogenic gene that promotes the occurrence of uterine fibroids." (PMID 35071776, 2022). "We also analysed SNPs on driver genes such as MED12, FH, and HMGA2 which harbor somatic mutations in uterine leiomyoma." (PMID 31988393, 2020). "The precise diagnosis of uterine leiomyomas can be made when MED12 genetic findings are coupled with clinical, biochemical, and histopathological findings." (PMID 30619444, 2018). "Mutations in exon 2 showed a particularly high rate of somatic alterations (70% of uterine leiomyomas) and have been shown to disrupt the direct interaction of MED12 with the cyclin C-CDK8 leading to reduced Mediator activity." (PMID 27602765, 2016). "In line with our observations, MED12 was recently characterized as a tumor suppressor in uterine leiomyomas, prostate cancer, chronic lymphocytic leukemia and breast fibroadenoma." (PMID 27602765, 2016). "Recently, we demonstrated that exon 2 of the MED12 gene is somatically altered in up to 70 per cent of uterine leiomyomas in a series of Finnish (Caucasian) patients." (PMID 22182697, 2011). "Uterine leiomyomas (ULMs) are classified into those with and without MED12 mutations (MED12m(+) and MED12m(−), respectively)." (PMID 39845479, 2025). "It is well known that estrogen is strongly associated with the growth of all breast fibroadenomas, and mutation of MED12, essential for activating CDK8 kinase and also playing an important role in the development of uterine leiomyomas, is found in many of them." (PMID 40385736, 2025). "Unlike uterine leiomyomas, which frequently harbor MED12 exon 2 mutations, most IVLs display wild-type MED12 or distinct variants, suggesting a different molecular pathogenesis." (PMID 41463261, 2025). "Previous studies defined the proteome of uterine fibroids and established that increased POSTN production is a hallmark of uterine fibroids regardless of MED12 mutation status." (PMID 35585291, 2022). "We first examined the DNA methylome of the uterine fibroids with and without MED12 mutations (MED12m-positive uterine fibroids (n = 6) and MED12m-negative uterine fibroids (n = 12), respectively), and myometrium (n = 6)." (PMID 35618793, 2022). "Further studies are needed to identify the differences among the three subtypes of uterine fibroids without MED12 mutation." (PMID 35618793, 2022). "Expression of SRA1 was higher in uterine leiomyoma samples without MED12 mutations than in uterine leiomyoma samples harboring MED12 mutations." (PMID 34122542, 2021).
Uterine leiomyoma (continued). "We showed for the first time that the hsa_circ_0060927 was ectopically expressed in uterine leiomyoma compared to the adjacent tissues, and MED12 mutation did not have any significant effect on the expression of the targeted circular RNA." (PMID 31746073, 2020). "Aberrant function of MED12 has been shown to account for 70% of uterine leiomyomas." (PMID 31027501, 2019). "Our study, being the first one from Arab world, confirms the previous findings that somatic MED12 mutations are critical to development and progression of uterine leiomyomas irrespective of the ethnic background." (PMID 30619444, 2018). "On the other hand, mutations of MED12 have not been detected in uterine leiomyomas with 12q14∼15 rearrangements resulting in overexpression of HMGA2." (PMID 28591699, 2017). "There are some studies that revealed genetic alterations in patients with uterine leiomyomas—a chromosomal rearrangement of 12q14-15 reflecting the rearrangement of the HMGA2 allele and a mutation of mediator complex subunit 12 (MED12), a transcription factor gene." (PMID 27846844, 2016). "Mutations of MED12 have, on the other hand, not been detected in uterine leiomyomas with 12q14~15 rearrangements resulting in overexpression of HMGA2." (PMID 25621995, 2015). "None of the tumours harboured mutations, indicating that aberrant hormonal function is not the underlying cause, at least alone, for MED12 mutations in uterine leiomyomas." (PMID 23132392, 2012). "Overall, the low frequency of MED12 exon 2 mutations in various mesenchymal tumours suggests that the high mutation frequency observed in uterine leiomyomas is not a common feature for all mesenchymal tumours." (PMID 23132392, 2012). "Mediator complex subunit 12 had not been implicated in human tumorigenesis before identification of specific exon 2 mutations in uterine leiomyomas." (PMID 23132392, 2012). "Furthermore, MED12 mutants synergize with PR in uterine leiomyoma stem cell proliferation." (PMID 40940746, 2025). "Furthermore, the MED12 gene is closely related to uterine leiomyoma." (PMID 37810911, 2023). "However, the remaining 30% of uterine fibroids do not have MED12 mutations, which indicates that the role of MED12 mutations in the pathogenesis of uterine fibroids is unclear." (PMID 35618793, 2022). "Because uterine leiomyomas with MED12 mutations expressed significantly higher levels of the gene encoding wingless-type MMTV integration site family, member 4 (WNT4), the authors suggested that the MED12 mutations exert their effects by activating the canonical Wnt pathway." (PMID 25621995, 2015). "In this study we created 15-state chromatin annotations for myometrium, and MED12, HMGA2, and FH uterine leiomyomas." (PMID 40341524, 2025). "To know whether mutations in MED12 are associated with the upregulation of upstream regulators, SATB2 and NRG1 in uterine fibroids, we examined the DNA methylation and expression levels of SATB2 and NRG1 in the uterine fibroids with and without MED12 mutations." (PMID 35618793, 2022). "Alterations of mediator complex subunit 12 (MED12) and high mobility group AT-hook 2 (HMGA2) are the most common genetic aberrations in uterine leiomyomas." (PMID 31027501, 2019). "While alterations of MED12 and HMGA2 are most common in uterine leiomyomas, a range of other genetic pathways have been described." (PMID 31027501, 2019). "However, one study on SD rats model of uterine fibroids and human uterine leiomyoma cells demonstrated that GZFL inhibited uterine fibroids growth by modulating Mediator complex subunit 12 (Med12)-mediated wingless-type (Wnt)/β-Catenin signaling pathway." (PMID 35529925, 2022). "Mutations of mediator subcomplex 12 (MED12) and of high mobility group protein AT-hook 2 (HMGA2) are driver mutations in uterine leiomyomas (UL) that have not been observed to coexist in one tumor and even rarely coexist in different UL tumors of one patient." (PMID 26468330, 2015).